AAK1 (AP2 associated kinase 1)
Diseases named in the same sentence as AAK1 in open-access papers (continued):
Sharing a sentence is not in itself a finding about the gene and the disease.
infection (9 papers, 2016 to 2025). The state of being infected such as from the introduction of a foreign agent such as serum, vaccine, antigenic substance or organism. "The knockdown of AP2-associated kinase 1 (AAK1) significantly decreased the infection of cells by Rabies virus (RABV)." (PMID 40431739, 2025). "We also detected extensive downregulation of AAK1 phosphorylation on sites T568 and S572 upon infection with all variants." (PMID 39653747, 2024). "We also showed that AAK1 plays a critical role in infection by vesicular stomatitis virus (VSV), which is another rhabdovirus." (PMID 32872567, 2020). "A growth kinetic assay with recombinant RABV ERA-mCherry (mCherry gene inserted between ERA M and G gene as an additional transcription unit) showed that the AAK1 knock-down inhibited RABV infection in HEK293 cells post-transfection." (PMID 31905947, 2019). "AAK1 knock-down greatly inhibits RABV infection of cells, and AAK1-induced phosphorylation of threonine 156 of the μ subunit of adaptor protein 2 (AP2M1) is found to be required for RABV entry." (PMID 31905947, 2019). "The morphological changes in C. elegans with A. dhakensis AAK1 infection were observed by TEM and SEM." (PMID 28101079, 2016). "Furthermore, inhibition of AAK1 and GAK was shown previously to inhibit infection of many pathogenic viruses, highlighting them as potential targets for broad-spectrum antivirals." (PMID 39017647, 2024). "In addition, AAK1 knockdown decreased infection in N2a cells by vesicular stomatitis virus, which is another rhabdovirus." (PMID 32872567, 2020). "In addition, sunitinib treatment of cells inhibited RABV CVS-11 strain infection, which further indicates that AAK1 contributes to RABV infection in a RABV strain-independent manner." (PMID 32872567, 2020). "Knock-down of AAK1 significantly decreased the infection of cells by RABV." (PMID 31905947, 2019). "The results showed that ERA-mCherry infection was completely restored by AAK1 cDNA transfection." (PMID 31905947, 2019). "We found that although the addition of sunitinib inhibited RABV infection at all time points (from -1 to 9 h), but the strongest inhibitory effect appeared at -1 and 0 h post-infection, indicating that inhibition of AAK1 mainly affected the very early stage of RABV infection." (PMID 31905947, 2019). "Taken together, A. dhakensis AAK1 infection can induce riok-1 expression in C. elegans." (PMID 29719537, 2018). "Furthermore, AAK1 knockout prevented RABV rHEP-GFP strain infection." (PMID 32872567, 2020). "In addition, the riok-1 expression level induced by A. dhakensis AAK1 infection in the wild-type N2 worms was significantly higher than those in the pmk-1(km25) mutants, suggesting the coexistence of another pathway that is independent of p38 MAPK-regulated activation of riok-1 expression." (PMID 29719537, 2018). "We found that AAK1 is essential for TOSV infection while GAK appears to play a less critical role, as evidenced by the increased infection levels observed at a higher MOI in shGAK cells but not in shAAK1 cells and the lack of effect of erlotinib." (PMID 39017647, 2024).
tumor (7 papers, 2020 to 2025). "Also enriched in this cluster was the natural killer triggering receptor NKTR, associated with IL-2 activation, and AAK1, implicated in chemokine receptor expression and trafficking to the tumor microenvironment." (PMID 38566989, 2024). "Knockout of AAK1 significantly inhibited ferroptosis and lipid peroxidation, thereby promoting tumor growth." (PMID 41407700, 2025). "Here the authors revealed that PKCβII facilitates the endocytosis of TFR1 and increases cellular iron levels through the phosphorylation of AAK1, thus promoting ferroptosis of tumor cells." (PMID 41407700, 2025). "We also demonstrate that PKCβII promotes the endocytosis of TFR1 through the phosphorylation of AAK1, thereby facilitating ferroptosis and inhibiting tumor growth in vivo, which presents a potential therapeutic target for ferroptosis in clinical treatment." (PMID 41407700, 2025). "In this study, we found that PKCβII facilitates clathrin-mediated endocytosis of TFR1 and increases cellular iron levels through the phosphorylation of AAK1, thus promoting ferroptosis of tumor cells." (PMID 41407700, 2025). "While research on the role of AAK1 in tumor progression remains limited, previous study has suggested that AAK1 can stimulate the Notch pathway." (PMID 38169546, 2024). "To further confirm the therapeutic potential of targeting AAK1 in OV in vivo, we created xenograft tumor models and tumor metastasis assays." (PMID 38169546, 2024). "Furthermore, knockdown of AAK1 significantly inhibited tumor growth and weight, decreased lung metastases, and ultimately extended the survival time of the nude mice." (PMID 38169546, 2024). "While there is a slightly higher tumor mutational burden in EPAS1-altered tumors (9.9 vs. 4.9 mut/Mb), they are enriched in and associated with genes promoting immune evasion, including ARID5B, SPINT1, AAK1, CLIC3, SORT1, SASH1, and FGFR3, respectively (q < 0.001)." (PMID 36421334, 2022). "As expected, knockout of AAK1 significantly inhibited ferroptosis through resistance of lipid peroxidation induced by IKE and promoted tumor growth." (PMID 41407700, 2025). "In the subsequent analysis, the infiltration characteristics of immune cells in the tumor tissue of LUAD patients were revealed to be closely related to the expression levels of ACE2, TMPRSS, and AAK1." (PMID 33195212, 2020). "To further confirm the role of AAK1 during the process of ferroptosis in vivo, we performed xenograft tumor model by inoculating AAK1-knockout MDA-MB-231 cells with or without transfecting plasmids of wild-type or S670/T674Ala mutant AAK1 into nude mice." (PMID 41407700, 2025). "In addition, knockout of AAK1 also remarkably inhibited lipid peroxidation under BSO-mediated ferroptosis and promoted tumor growth in nude mice xenograft model." (PMID 41407700, 2025). "Knockdown of AAK1 substantially suppressed tumor growth, tumor weight, as well as the expression of AKK1, Notch3, GLS, MMP-2, MMP-9, and Ki-67 percentage." (PMID 38169546, 2024). "The ablation of AAK1 or non-phosphorylatable mutants blocking the PKCβII-AAK1-AP2M1 axis can effectively inhibit ferroptosis in vivo and promote tumor growth." (PMID 41407700, 2025).
neurodegenerative disease (3 papers, 2014 to 2022). A disorder of the central nervous system characterized by gradual and progressive loss of neural tissue and neurologic function. "Our study further suggests a link between AAK1 and ALS pathology, expanding its role to yet another neurodegenerative disease." (PMID 25514244, 2014). "Collectively, our study is the first to show the functional epigenic regulation of the ZFAS1/miR-4711-5p/AAK1 axis in cell apoptosis and ECM degradation under the IDD condition, which may provide new understanding of the pathogenesis of degenerative disease." (PMID 36561842, 2022).
neurological disorders (3 papers, 2018 to 2024). "Adaptor Associated Kinase 1 (AAK1) plays an important role in the treatment of nervous system diseases." (PMID 37955299, 2023). "AAK1 has been proposed as a potential drug target for treating various neurological disorders and preventing viral entry, where kinase activity is the target of inhibition." (PMID 39028260, 2024). "The reason why AAK1 can play an important role in nervous system diseases is that AAK1 participates in many nervous system-related signal pathways, such as NDR and CDK signal pathways." (PMID 37955299, 2023). "Compound 7745 is an imidazo[1,2-b]pyridazine-based molecule originally developed to modulate AAK1 activity as a potential treatment of neurological disorders (Kd = 1 nM; 50% inhibitory concentration, <10 nM)." (PMID 29535204, 2018). "Indeed, intervention in AAK1 phosphorylation has been shown useful in clinical trials for the treatment of neurological diseases such as neurological pain, AD, Schizophrenia, and ALS." (PMID 37955299, 2023). "Because endocytosis is closely related to many pathophysiological functions of the nervous system, and AAK1 closely regulates the steps endocytosis, we hypothesise that AAK1 may affect cellular function by participating in the pathological development of some nervous system diseases." (PMID 37955299, 2023).
AAK1 also shares sentences with these, for which no sentence is quoted: Alzheimer disease (2 papers); co-infection (1); colorectal cancer (1); dental caries (1); Ebola (1); hearing loss (1); heart failure (1); Hypertension (1); Insulin resistance (1); intervertebral disc degeneration (1); kidney failure (1); leprosy (1); liver carcinoma (1); lung carcinoma (1); lung squamous cell carcinoma (1); nephritis (1); nephrosis (1); non-small cell lung carcinoma (1); ovarian carcinoma (1); Parkinson (1); periodontitis (1); pheochromocytoma (1); pulmonary hypertension (1); schizophrenia (1); Stroke (1); thyroid cancer (1); viral diseases (1); viral pneumonia (1).